HMGB1 (high mobility group box 1)
Diseases named in the same sentence as HMGB1 in open-access papers (continued):
Sharing a sentence is not in itself a finding about the gene and the disease.
atherosclerosis (continued). "HMGB1 is an inflammatory factor that increase VSMC proliferation and high glucose–induced calcification in VSMC and subsequent vascular inflammation and atherosclerosis." (PMID 32208365, 2020). "Combination of CXCL4 and CCL5 was shown to exacerbate disease in a mouse model of atherosclerosis, and CXCL12 in combination with HMGB1 enhanced monocyte recruitment in a mouse model of tissue damage." (PMID 33123134, 2020). "High-mobility group box 1 (HMGB1), is a crucial inflammatory factor in atherosclerosis, and a danger signal for vascular disease." (PMID 32208365, 2020). "High mobility group box 1 (HMGB1) is a ubiquitous and abundant nuclear protein with a critical role in many cardiovascular diseases, such as atherosclerosis, MI, myocardial I/R injury, and heart failure." (PMID 32063860, 2019). "Recently, we genetically modified MSCs with high mobility group box 1 (HMGB1) and demonstrated the high efficacy of these cells in treating graft atherosclerosis." (PMID 30867070, 2019). "Our results revealed that HMGB1 is a critical signal for TLR4-mediated the down-regulation of PPARγ/LXRα-ABCA1, which accelerates CUMS-induced atherosclerosis." (PMID 30881312, 2019). "Both HMGB1 and RAGE are highly expressed in atherosclerotic plaques to accelerate the progression of atherosclerosis." (PMID 29615103, 2018). "In this review, we look at the mechanisms of secretion of HMGB1, the role of receptors, MMP enzymes, hypoglycemia, atherosclerosis, edema, angiogenesis as well as neuroimmunological reactions and post-ischemic brain recovery in IS." (PMID 29054968, 2017). "In this study, we evaluated HMGB1 and sRAGE levels in GPA patients who had been enrolled in a follow-up study to evaluate progression of atherosclerosis." (PMID 24776932, 2014). "HMGB1 is a DAMP molecule that participates in the pathogenesis of arthritis and atherosclerosis by regulating immune response." (PMID 22808256, 2012). "HMGB1 is involved in LDL transport through the SREBP2 (sterol regulatory element binding protein 2)-SR-BI (scavenger receptor class B type 1) axis and contributes to atherosclerosis." (PMID 38740617, 2025). "At the organ level, DAMP-induced TLR signaling drives pathology across systems: TLR4 activation accelerates atherosclerosis, HMGB1 promotes plaque instability, and microglial TLR4 activation by HMGB1 or S100 proteins fuels neuroinflammation and cognitive decline." (PMID 41373468, 2025). "Similar signaling pathways may have been involved in the study of the cellular model of atherosclerosis (HAECs cells), in which the suppressed expression of HMGB1 (high-mobility group box 1) was observed." (PMID 39408653, 2024). "Taking into consideration the pro-inflammatory nature of HMGB1, these findings could indicate that HMGB is strongly involved in the background mechanisms driving the progression of atherosclerosis." (PMID 39194749, 2024). "Currently, there are no reports on macrophage-EVs' impact in regulating HMGB1 and the development of atherosclerosis." (PMID 38493291, 2024). "An example is HMGB1, the intranuclear non-histone DNA binding protein, which contributes to the stabilization of nucleosomes and the development of atherosclerosis." (PMID 36982889, 2023). "Although the exact mechanism has not been fully elucidated, the HMGB1/TLR4/MyD88 signaling pathway appears to be a new target for SLE combined with atherosclerosis treatment." (PMID 35571092, 2022). "Interestingly, exosomes released from platelets stimulated with thrombin and collagen present an increased amount of chemokines CXCL4, CXCL7, and cytoplasmic high-mobility group box 1 (HMGB1) protein, which contribute to the pathogenesis of atherosclerosis." (PMID 31212641, 2019). "Therefore, our present work was the first to reveal that enhancing HMGB1/TLR4 signaling induced by CUMS declined the expression of ABCA1 in aorta, leading to the development of atherosclerosis as confirmed by aortic sinus Oil Red O staining." (PMID 30881312, 2019).
atherosclerosis (continued). "Blocking HMGB1 release by EP or inhibiting TLR4 activation by TAK-242 almost reversed CUMS-induced the drownregulation of PPARγ-LXRα-ABCA1 and impeded the development of atherosclerosis in apoE-/- mice." (PMID 30881312, 2019). "Additionally, we injected inflammatory proteins directly into the endothelium of the vessel, which is the site of HMGB1 and TNF-α participation in early mechanisms of atherosclerosis." (PMID 29561847, 2018). "We used two inflammatory proteins, HMGB1 and TNF-α, which induce early atherosclerosis." (PMID 29561847, 2018). "Released HMGB1 interacts with RAGE, one of the main signaling pathways triggered in sustained inflammatory related diseases, and TNF-α is a potent pro-inflammatory cytokine that can induce atherosclerosis." (PMID 29561847, 2018). "As another possible mechanism for defective efferocytosis, the pro-inflammatory molecule high-mobility group box 1 (HMGB1) is increased in human and murine atherosclerosis, and the secreted form has been shown to interact with integrin αVβ3 and PtdSer to block efferocytosis." (PMID 29379788, 2017). "The understanding of pathophysiological mechanisms and of molecular pathways responsible for HMGB-1 and OPG involvement in atherosclerosis disease may provide us new therapeutic weapons to manage diabetic complications and morbidities." (PMID 28789654, 2017). "Interestingly, endogenous molecules such as high mobility group box 1 (HMGB1) can activate TLR4, which serves as a late mediator of inflammation and contribute to the development of atherosclerosis." (PMID 27563891, 2016). "Our present data suggest that HMGB-1 activates MT1-MMP through RAGE lead ing to RhoA/Rac1 activation, NF-κB phosphorylation and TF protein upregulation as a pathology of the progression of atherosclerosis and vascular endothelial dysfunction." (PMID 25490770, 2014). "Therefore, in the present study, we aimed to clarify the role of HMGB-1 and RAGE-MT1-MMP axis on signal transduction and the development of atherosclerosis." (PMID 25490770, 2014). "HMGB1 and RAGE also contribute to the pathogenesis of atherosclerosis." (PMID 24065095, 2013). "These numerous observations indicate that HMGB1 released from C. pneumoniae infected HAEC may be a possible mediator and enhancer of local inflammation and progression of atherosclerosis." (PMID 18284660, 2008). "Thus, while only inducing modest inflammatory responses by endothelial cells, Calprotectin and Hsp70, but not HA or HMGB-1, showed the capacity to disturb the endothelial barrier, a first step towards atherosclerosis, PVD and CAD." (PMID 37849759, 2023). "Furthermore hyperglycemia acts directly on HMGB1 release which enhances ROS production, endothelial cells dysfunction and VSMCs damage; HMGB1 acts in synergy with TLRs and RAGE, promoting progression of atherosclerosis and DM vascular complications." (PMID 31835864, 2019). "The interaction between HMGB1 and its receptors (particularly, RAGE and TLRs) enhances both inflammatory response and immune response, elements that promote cellular damage and vascular dysfunction, leading to development of atherosclerosis and complications of DM." (PMID 31835864, 2019). "Our mAb recognizes the C-terminal sequence of the HMGB1 molecule and can neutralize the intercellular adhesion molecule 1 (ICAM1)-inducing activity of HMGB1 in vitro;19 moreover, therapeutic effects against brain stroke, atherosclerosis, and viral infections have also been reported." (PMID 28649578, 2017). "Exposure of Human Aortic Endothelial Cells (HAEC) to Calprotectin, HA and HMGB-1, as well as all CKD-DAMPs combined, but not to Hsp70, led to a modest increase in MCP-1, a major monocyte chemoattractant expressed at atherosclerosis plaques." (PMID 37849759, 2023).
endotoxemia (112 papers, 2007 to 2025). "In our study, the increase in liver GSDMD activation preceded the increase in circulating HMGB1 levels during endotoxemia, and hepatocyte-specific Gsdmd deficiency decreased the plasma HMGB1 concentration and improved the survival of mice from 10% to 100%." (PMID 39927458, 2025). "In contrast to pyroptosis mediated by GSDMD‐induced release of HMGB1 in macrophages, GSDMD‐deficient mice typically release HMGB1 during endotoxemia." (PMID 38020710, 2023). "Deletion of HMGB1 in hepatocytes or neutralizing HMGB1 with monoclonal antibodies phenocopies caspase-11- or GSDMD-deficiency in endotoxemia and bacterial sepsis." (PMID 33854044, 2021). "High mobility group box-1 has been shown to act as a mediator of endotoxemia in mice and is regarded as a damage-associated molecular pattern (DAMP) molecule, causing inflammatory responses in various diseases." (PMID 34867200, 2021). "The inhibitory effects ofmetformin on inflammation in lipopolysaccharide-treatedcells and endotoxemia in mice were shown to be inducedby inhibiting the release of HMGB1 a prominent proinflammatorycytokine and damage associated molecularpattern (DAMP)." (PMID 32779431, 2020). "The pathogenic role of HMGB1 in endotoxemia was inferred from studies using HMGB1-neutralizing antibodies, which conferred a dose-dependent protection against endotoxin-induced tissue injury and lethality." (PMID 26257917, 2015). "Application of lower doses HMGB1 in vivo (10 to 50 μg/mouse) caused similar symptoms as observed in animals with systemic inflammatory syndrome e.g. after endotoxemia." (PMID 22514737, 2012). "Hepatocyte Hmgb1 deficiency prevents vascular injury and death in endotoxemia." (PMID 39927458, 2025). "Released HMGB1 is also an inflammatory mediator with cytokine activity that emphasizes the production of inflammatory cytokines of intestinal inflammation associated with endotoxemia and NEC." (PMID 36768650, 2023). "Taken together, our findings indicate that natural compounds, including those of the herb C. longa, that may prevent HMGB1 production and/or activity may aid the treatment of inflammation-associated disorders such as endotoxemia." (PMID 28929026, 2017). "Another factor responsible for cardiac contractile dysfunction associated with endotoxemia is HMGB1, a damage-associated molecular pattern molecule that is actively secreted by stimulated immune cells and passively released by nonimmune cells undergoing necrosis." (PMID 26635633, 2015). "However, the effect of GL on HMGB1 expression in endotoxemia as well as its underlying molecular mechanism remained unclear." (PMID 23497622, 2013). "Thus, hepatocyte-derived HMGB1 causes systemic vascular injury and death in endotoxemia." (PMID 39927458, 2025). "Serum levels of HMGB1 significantly increase 16 to 32 hours following systemic lipopolysaccharide challenge in mice, and a systemic injection of the recombinant HMGB1 in mice is lethal, two findings that provide further support for the pathogenic role of HMGB1 in endotoxemia." (PMID 23351605, 2013). "Although anti-HMGB1 antibodies have shown protective effects in improving survival during endotoxemia in mice, their application in animal models remains limited due to concerns regarding safety and efficacy." (PMID 40430548, 2025). "Collectively, the results of the in vivo experiments suggest that endothelial GSDMD-mediated systemic vascular injury and lethality are dependent on hepatocytic GSDMD-mediated HMGB1 release in endotoxemia." (PMID 39927458, 2025). "Hepatocyte GSDMD regulates endothelial GSDMD-mediated vascular injury in an HMGB1-dependent manner in endotoxemia." (PMID 39927458, 2025). "High extracellular HMGB1 levels trigger a pro-inflammatory cytokine cascade and are pivotal in the pathogenesis of acute lung injury and leading to lethal endotoxemia." (PMID 41472211, 2025). "As a late mediator of inflammation, HMGB1 is released during the advanced stages of endotoxemia in rodents." (PMID 40430548, 2025).
endotoxemia (continued). "Passive immunization with anti-HMGB1 antibodies significantly protects against lethal endotoxemia in mice, even when treatment was delayed 2 h after LPS exposure." (PMID 39849347, 2025). "In murine endotoxemia and bacterial sepsis models, HMGB1 binds LPS which is subsequently recognised and internalised by receptor for advanced glycation end products (RAGE)-mediated endocytosis." (PMID 35712726, 2022). "In murine models of endotoxemia induced by intraperitoneal injection of LPS, HMGB1 reaches plateau levels from 16 to 32 h." (PMID 36552192, 2022). "Earlier studies demonstrated that metformin reduced mortality in a mouse model of lethal endotoxemia by inhibiting HMGB1 release; inhibition of NF-κB-induced TNF-α activation and AMPK activation were the mechanisms contributing to the protective effects." (PMID 35156512, 2022). "In mice, inhibition of HMGB1 activity via antibody targeting revealed a protective effect against lipopolysaccharide (LPS) lethality, whereas increasing HMGB1 activity resulted in worsened endotoxemia and LPS lethality." (PMID 35392093, 2022). "Loss of hepatocyte HMGB1, inhibition of hepatocyte HMGB1 release, neutralization of extracellular HMGB1 or RAGE deficiency can prevent caspase-11-dependent pyroptosis and death in endotoxemia and bacterial sepsis." (PMID 35720285, 2022). "In endotoxemia and bacterial sepsis, HMGB1 released by hepatocytes is necessary for caspase-11 dependent pyroptosis and mortality." (PMID 35720285, 2022). "Another protein that has been demonstrated as a key requisite for caspase-11 mediated pyroptosis and lethality in endotoxemia and bacterial sepsis is hepatocyte-released high mobility group box 1 (HMGB1) protein." (PMID 33546173, 2021). "Wang showed that treatment of FeTPPS (a small molecule selectively inhibits HMGB1- mediated caspase-11 activation) attenuates HMGB1- and caspase-11-mediated immune responses, organ damage, and lethality in endotoxemia and bacterial sepsis." (PMID 34743181, 2021). "Our seminal discovery of HMGB1 as a late mediator of lethal endotoxemia has stimulated extensive interest in search for HMGB1-targeting pharmacological inhibitors ranging from small molecules to large biological agents." (PMID 34571869, 2021). "Inhibition of HMGB1–LPS binding and neutralizing extracellular HMGB1 prevents caspase-11–dependent pyroptosis and death in endotoxemia." (PMID 34093202, 2021). "In an animal model of lethal endotoxemia, circulating fetuin-A levels were decreased in an anti-parallel fashion when circulating HMGB1 levels were elevated." (PMID 34571869, 2021). "Most importantly, exposure to anti-HMGB1 prior to LPS administration in mice strongly reduces LPS-induced lethality, thereby demonstrating the permissive role of HMGB1 in endotoxemia-induced inflammation." (PMID 34685561, 2021). "Taken together, these observations indicated that FeTPPS attenuates caspase-11 activation in vivo, which is driven by hepatocyte-released HMGB1 in endotoxemia or bacterial sepsis." (PMID 33854044, 2021). "Treatment of FeTPPS significantly attenuates HMGB1- and caspase-11-mediated immune responses, organ damage, and lethality in endotoxemia and bacterial sepsis." (PMID 33854044, 2021). "In previous studies, it has been shown that LPS- and ATP-induced HMGB1 release is inhibited in macrophage cultures and endotoxemia models due to genetic deletion of NLRP3 or ASC, which are the main components of the NLRP3 inflammatory model." (PMID 34066647, 2021). "In a murine model of endotoxemia induced by intraperitoneal administration of LPS, HMGB1 was first detected in the circulation eight hours after endotoxemia, and subsequently increased to plateau levels from 16 to 32 hours." (PMID 34571869, 2021). "In an animal model of lethal endotoxemia, HMGB1-specific polyclonal antibodies were protective in a dose-dependent fashion." (PMID 34571869, 2021).
endotoxemia (continued). "This late appearance of circulating HMGB1 paralleled with the onset of animal lethality from endotoxemia, and distinguished itself from TNF and other early proinflammatory cytokines." (PMID 34571869, 2021). "When looking at murine models of bacterial sepsis and lethal endotoxemia, HMGB1 must therefore be considered an important regulator of LPS-induced caspase-11 activation." (PMID 33546173, 2021). "HMGB1 release during endotoxemia was caspase-11/GsdmD dependent via an active way in vivo and in vitro." (PMID 32328059, 2020). "Here, we confirmed that hepatocytes are the dominant source of the increases in circulating HMGB1 during endotoxemia." (PMID 32328059, 2020). "This unconventional secretion pathway is notable in that in a reciprocal relationship, cytosolic HMGB1 has been shown to be protective against endotoxemia and bacterial infection via its interaction with the autophagy pathway." (PMID 32917873, 2020). "During endotoxemia, gasdermin D knockout mice secrete HMGB1 normally, yet secretion of IL-1β is completely blocked." (PMID 32917873, 2020). "It was first demonstrated that HMGB1, acting through RAGE and dynamin-dependent signaling, is required for HMGB1 endocytosis, which in turn induces macrophage pyroptosis which occurs in vitro and also in vivo during endotoxemia." (PMID 30975096, 2019). "Blockade of HMGB1 via antibody targeting protects against LPS lethality in mice, whereas administration of HMGB1 in mice results in developing endotoxemia and lethality." (PMID 31402909, 2019). "Neutralizing extracellular HMGB1 with monoclonal antibodies confers considerate protection against Caspase-1/Caspase-11-mediated lethality during endotoxemia." (PMID 30134814, 2018). "Neutralizing the extracellular HMGB1 using anti-HMGB1 monoclonal antibodies significantly increased the survival during lethal endotoxemia or bacterial sepsis." (PMID 30134814, 2018). "Endogenous neuropeptides, specifically vasoactive intestinal peptide (VIP) and urocortin, acted as inhibitors of HMGB1 cytokine activity that increased the survival of animals with established endotoxemia." (PMID 28127491, 2017). "Here, we report that a D. odorifera extract (DOE) inhibited LPS-triggered release of HMGB1 in macrophages and an animal model of endotoxemia." (PMID 28403838, 2017). "These steroid derivatives significantly protected mice against lethal endotoxemia by selectively blocking the endotoxin-induced cytoplasmic translocation and release of HMGB1." (PMID 28127491, 2017). "The present observation is consistent with previous reports in which blockade of HMGB1 attenuated endotoxin lethality in a mouse model of endotoxemia, even when administered after LPS injection." (PMID 28403838, 2017). "Our previous study demonstrated that the PKM2 inhibitor shikonin inhibits PKM2 activity and suppresses circulating IL-1β and HMGB1 levels and prevents lethality during endotoxemia and polymicrobial sepsis in mice." (PMID 27779186, 2016). "In mouse models of lethal endotoxemia, shikonin reduced serum levels of an inflammatory mediator high-mobility group box 1 (HMGB1) protein and protected mice from LPS-induced death." (PMID 27467658, 2016). "In the other study, results obtained from HMGB1 conditional knockout mice showed that myeloid HMGB1 contributes to protection from endotoxemia and bacterial infection in mice." (PMID 27311356, 2016). "In contrast to its delayed release following endotoxemia and microbial infection, HMGB1 is rapidly released subsequent to tissue I/R injury." (PMID 25780465, 2015). "Blocking HMGB1 activity reduces mortality in an animal endotoxemia model, even when administered late during the course of the disorder." (PMID 23874764, 2013). "Expression levels of HMGB1 mRNA and protein in lungs, liver, kidneys, small intestine and lymph node were enhanced markedly after endotoxemia compared with the sham group." (PMID 23497622, 2013).